ATR (ATR checkpoint kinase)
Diseases named in the same sentence as ATR in open-access papers (continued):
Sharing a sentence is not in itself a finding about the gene and the disease.
cancer (continued). "In case of treated C33A cells, however, p-ATR and p-Chk1 expressions were increased by 0.7 fold and 0.6 fold respectively.This clearly indicate that, LRF induced ROS can cause DNA damage in these cancer cells." (PMID 31628385, 2019). "Although ATR and Chk1 inhibitors are being evaluated in multiple clinical trials, the genetic predispositions that would sensitise or desensitise cancer cells to ATR and Chk1 inhibitors are not fully elucidated." (PMID 31424118, 2019). "However, FOXO3 has been reported to regulate many genes involved in cancer development, such as p21, ATR, ΔNp63, and VEGF." (PMID 31013711, 2019). "For these reasons, ATR is an attractive target to disrupt DNA repair in cancer cells." (PMID 30714316, 2019). "Combining ATR inhibitors with DNA-damaging radiation or chemotherapy could lead to synthetic lethality, particularly in cancer cells that harbor overexpression of oncogenes like Myc." (PMID 31018854, 2019). "Preclinical studies have shown that cancer cells with defective DNA repair mechanisms or cell cycle checkpoints may be particularly sensitive to ATR inhibitors." (PMID 31018854, 2019). "Notably, some ATR inhibitors have been already tested in vivo for cancer treatment with encouraging results." (PMID 30871494, 2019). "This suggests that targeting ATR-mediated RRM2 phosphorylation may represent a potential new therapeutic strategy for cancer therapy." (PMID 31324785, 2019). "As ATR inhibition is a promising anti-cancer approach, whether combining ATR inhibitor with endocrine therapy in MYC amplified tumours will be clinically relevant will be an interesting area for future investigation." (PMID 30746633, 2019). "To determine how Claspin, Timeless, and CHK1 could promote tolerance to RS independently of ATR signaling, we first checked their protein levels in cancer cell lines and immortalized primary cells." (PMID 30796221, 2019). "Indeed, as a proof-of-principle, we have demonstrated that RAD52 inhibition potentiates the effects of an ATR inhibitor in cancer cells." (PMID 29695617, 2018). "Based on several studies, ATR is not mutated in the vast majority of human cancers, including breast and ovarian carcinomas." (PMID 30410668, 2018). "This is because there is great current interest in the anti-cancer therapeutic potential of both replication stress targeting agents such as ATR inhibitors and in epigenetic therapies, which may, for example, inhibit histone methylation or deacetylation." (PMID 30544989, 2018). "Consequently, cancer cells are particularly vulnerable to ATR inhibitors and they are being developed as cancer therapeutics." (PMID 29720710, 2018). "Increased replication stress enhances the dependency of cancer cells on ATR and CHK1." (PMID 29720710, 2018). "Furthermore, the DNA2 inhibitor C5 mimics DNA2 knockout and synergistically kills cancer cells when combined with an ATR inhibitor." (PMID 29773570, 2018). "However, how replication stress induces extensive activation of ATR-Chk1 signaling for DNA damage tolerance in cancer still is needed to explore." (PMID 29209046, 2017). "Notably, two trunk genes (SPEN and ITK), a branch gene (SMARCE1), and several private genes (FAT4, CACNA1D, ATR, RUNX1T1, TERT, and SRGAP3) were defined as cancer-associated genes, according to the cancer gene census." (PMID 28716121, 2017). "We assume that elevated expression levels of ATR and WRN might be linked to longevity and cancer resistance in Spalax, given that Heterocephalus also showed higher expression of these two genes." (PMID 29084988, 2017). "However, as Eμ-MYC AtrS/S mice display drastically reduced lifespan and die of pleiotropic disease, this study failed to unambiguously separate the consequences of impaired ATR from impaired downstream CHK1 signaling for cancer formation." (PMID 29167438, 2017).
cancer (continued). "The PARP and ATM/ATR inhibitors are currently the most promising novel agents undergoing investigation in these solid tumours, as DDR seems to be affected in most of these germline-mutated or BRCA-like cancers." (PMID 29069866, 2017). "We and others have reported that the inhibition of ATR-Chk1 pathways could sensitize cancer cells to cisplatin treatment." (PMID 26657501, 2016). "It has been shown that targeting the ATR pathway is a promising strategy for cancer therapy." (PMID 27145275, 2016). "Therefore, targeting ATR/chk1 pathways is a useful strategy for enhancing the cancer-selective killing efficacy of DNA-damaging agents." (PMID 27246979, 2016). "So inhibition of Cdc6 may be a new promising strategy to inhibit ATR pathway for killing CDDP-resistant cancer cells." (PMID 27246979, 2016). "The cell death induced by ATR inhibitors is highly selective for cancer cells that rely on ALT, suggesting that such inhibitors may be useful for treatment of ALT-positive cancers." (PMID 26918938, 2016). "A recent paper showed that cancer cells bearing ALT telomeres are sensitive to ATR inhibitors." (PMID 26990647, 2016). "It has been hypothesized that cancer cells mainly rely on the ATR/Chk1 pathway to repair DNA damage." (PMID 27246979, 2016). "Our results indicated that NTP or NTPO treatment in human cancer cells could induce ATR-mediated cell-cycle checkpoints and PARP1-dependent DNA repair." (PMID 27145275, 2016). "On the other hand, ATR, Chk1, and Wee1 are also overexpressed in a subset of human cancers." (PMID 25774168, 2015). "VE-821 was the first specific and potent ATR inhibitor that abrogated G2/M checkpoint and reduced survival of various cancer cell lines after radiotherapy or treatment with chemotherapeutics including cisplatin, etoposide, gemcitabine, neocarzinostatin, and camptothecin." (PMID 26295265, 2015). "Recently, ATR inhibitors showed to sensitize tumor cells to topoisomerase inhibitors already used in clinical trials, thus suggesting the possibility of a combined strategy to enhance cancer treatment efficacy." (PMID 26046463, 2015). "Inhibitors of ATR, Chk1, or Wee1 may thus potentially be more toxic to cancer cells inherently expressing high levels of these kinases." (PMID 25774168, 2015). "Consistent with this hypothesis, increased expression of ATR/Chk1/Wee1 kinases was reported in various cancer cell lines." (PMID 26295265, 2015). "Cancer cells with reduced expression of ATR were thus more sensitive to the ATR inhibitor." (PMID 25774168, 2015). "Therefore, a better understanding of the network of ATM/ATR-mediated prosurvival pathways in Drosophila ISCs shed insights into not only cancer therapy, but also how stem cell homeostasis is regulated in an aging gut, as shown in the present study." (PMID 26000719, 2015). "Indeed, several studies have demonstrated increased cytotoxic effects of both Chk1 and ATR inhibitors in cancer cells exposed to hypoxia compared to normoxic cells." (PMID 25774168, 2015). "TOPBP1 and ATR are amplified independently in 1 and 12 carcinomas, respectively." (PMID 26438152, 2015). "Naturally, the most desirable effect of ATR inhibition in cancer treatment is increased cell death." (PMID 25003641, 2014). "This dependence makes the ATR pathway a promising cancer therapeutic target." (PMID 24901225, 2014). "Therefore it fails to give a comprehensive view of the mechanisms of radiosensitization by ATR inhibition in the context of cancer cells." (PMID 25003641, 2014).
cancer (continued). "A recent discovery of the first selective inhibitors of ATR kinase facilitated investigation of the cellular functions of ATR and launched the development of new potential anti-cancer drugs targeting this kinase to sensitize cancer cells to chemo- or radiotherapy." (PMID 25003641, 2014). "In addition, we also investigated the ability of ATR inhibitors to potentiate cisplatin cytotoxicity in XRCC1 deficient and XRCC1 proficient CHO and human cancer cells." (PMID 23451157, 2013). "For example, ATM is critical for the mitotic checkpoint and its mutation is associated with human cancer, whereas ATR is not." (PMID 23251624, 2012). "Defective ATR pathway signaling could result in DNA breakage at these sites, and thus lead to cancer-specific chromosomal aberrations." (PMID 21286310, 2010). "The ATM and ATR pathway thus serves as a crucial cellular anti-cancer barrier." (PMID 18577246, 2008). "Nevertheless, cell lines with inactivated ATR exhibit genetic instability, which may suggest proneness to cancer." (PMID 15987455, 2005). "However, ATR, RASSF1, ACTN4, and MRTFA all harbor single-nucleotide polymorphisms (SNPs) that consistently associate with variations grouped into neurological, body fat, and cancer." (PMID 39951537, 2025). "Importantly, ATR’s effects on mTORC1 via cholesterol appear to be specific to cancer cells, which may indicate that these inhibitors will more specifically target cholesterol synthesis in cancer cells and not normal tissue." (PMID 40514450, 2025). "Similarly, the research "KLF5 loss sensitizes cells to ATR inhibition and is synthetic lethal with ARID1A deficiency" published on January 8, 2025, highlighted the potential of targeting the KLF5-ARID1A axis in cancer cells." (PMID 41542076, 2025). "Overall, this study represents a strategically adaptive platform to define optimal combination regimens of ATR inhibition and establish biologically active doses across diverse therapeutic contexts, ultimately informing subsequent biomarker-guided trials in molecularly defined cancer populations." (PMID 40869030, 2025). "Moreover, inhibitors of PARP, ATM and ATR may be able to take advantage of DNA-repair defects in cancer to increase genomic instability." (PMID 40565309, 2025). "Indeed, we propose that ATR inhibition could directly act on T cells potentially driving them towards a stem-like phenotype while simultaneously sensitizing cancer cells to oxaliplatin." (PMID 40139833, 2025). "Additionally, cancer cells may adapt by activating alternative DNA damage response pathways to withstand ATR inhibition." (PMID 40573290, 2025). "Interestingly, cholesterol supplementation did not rescue pS6K in normal cells upon ATR inhibition (Fig. EV4C,D), indicating that cancer cells can regulate mTORC1 via ATR and cholesterol, whereas normal cells may have an alternative pathway." (PMID 40514450, 2025). "There is also data arguing against this hypothesis, showing that upstream and downstream components of the ATR–Chk1 pathway are differentially regulated in primary cancer cells, and that Claspin, Tim, and Chk1 make part of a functional module that functions independently of the ATR axis." (PMID 41009395, 2025). "Since MYC-driven cancer cells are vulnerable to inhibition of Aurora A and ATR which suppress increases in R-loop, TRC, and DNA damage, MYC activation may not only cause transcription-associated RS but also elevate the tolerability for survival and growth under this stress." (PMID 39456601, 2024).
cancer (continued). "DNA damage induced by chemotherapy or radiotherapy simultaneously with ATR inhibition in the context of heightened levels of replication stress could overwhelm the ability of cancer cells to repair damaged DNA and lead to synergistic anti-cancer effects." (PMID 38195460, 2024). "Likewise, ATR is not as commonly mutated or depleted in cancer cells as has been observed for ATM (TCGA)." (PMID 39456630, 2024). "Indeed, ATR inhibition has shown promising antitumor efficacy in preclinical models and several ATR inhibitors (ATRi) have entered early phase clinical trials for different cancer subtypes." (PMID 38756373, 2024). "Furthermore, ATR inhibition may enhance tumor immunogenicity by reducing the expression of programmed cell death 1 ligand 1 (PD-L1) in irradiated cancer cells." (PMID 38474014, 2024). "While inhibiting ATR activity may induce replication fork stalling and collapse in normal cells, leading to some cytotoxicity, this cytotoxicity is further exacerbated in cancer cells with high replication stress." (PMID 39156700, 2024). "This may be reflective of selection on the basis of protein ATM expression, instead of selecting on the basis of ATM inactivating mutations, and/or may reflect the schedule of ATR inhibitor employed, with potentially more continuous schedules being more optimal for ATM-deficient cancers." (PMID 37773077, 2023). "Thus, combining ATR with Chk1 inhibition can be a rational approach to overcoming resistance to Wee1 inhibition, and it has demonstrated a synergistic anti-tumor effect in multiple types of cancer cells." (PMID 37296592, 2023). "We hypothesized that combining radiation with AZD6738, an inhibitor of ATR (ATRi), radiosensitizes cancer cells due to ATR's role in DNA repair and the cell cycle, and that this effect is greater for protons compared to photons due to the more complex DNA damage induced by protons." (PMID 36721481, 2023). "However, the occurrence of off-target effects caused by ATR and CHK1 inhibition could involve pathways other than the DDR and cause cell death in both normal and cancer cells." (PMID 37858134, 2023). "The combinational approach of PARP and ATR inhibition to enhance response to PARP inhibitors could expand the utility of PARP inhibitors to cancer patients without BRCA1/2 mutations." (PMID 36794257, 2023). "Considering the growing list of synthetic lethal gene pairs with ARID1A deficiency, it may be interesting to investigate the efficacy of combinational therapy of PLK1 inhibitor and agents targeting synthetic lethal phenotypes in ARID1A-mutated cancers, such as PARP inhibitors and ATR inhibitors." (PMID 36980292, 2023). "These cancer cells are expected to exhibit a vulnerability while they handle high levels of DNA replication stress, and exacerbating this replication stress using ATR inhibitors, or other checkpoint inhibitors that target CHK1 or WEE1, is thought to be a promising strategy for cancer therapy." (PMID 36892674, 2023). "Prior research has suggested that ATR inhibitors may have substantial efficacy in ATM-deficient cancers, yet in Cohort E we do not see strong evidence for activity in cancers with absent/low ATM expression." (PMID 37773077, 2023). "Furthermore, the significant impact of the ATR mutation in the response to SN-38 and VE-822 could open new doors in the management of ATR-mutated MSI + cancers." (PMID 35361811, 2022).
cancer (continued). "However, ATR inhibitor monotherapy in cancer cells has rarely been reported." (PMID 36539893, 2022). "Additionally, accumulating evidence reveals that p-ATR is overexpressed in several cancers." (PMID 35456022, 2022). "Studies have shown that disruption of ATR function through depletion or kinase-dead protein expression could influence the survival of several cancer cell lines, including osteosarcoma cancer cells, lung cancer cells, and colon cancer cells, with or without DNA-damaging agents." (PMID 36497387, 2022). "The biological consequence of the significant downregulation of ATM and ATR observed in Saos-2/CDDP-resistant variants is a relevant finding that needs to be further explored, since inhibitors against ATR have already been used in clinical trials in other cancers." (PMID 36233089, 2022). "Instead, treatment with these small molecule CB002-analogs results in activation of an S-phase DNA damage response pathway characterized by the increase in p-ATR and we suggest this ultimately leads to a delay of cells in S-phase and this S-phase perturbation may contribute to cancer cell death." (PMID 34324416, 2021). "Notably, cancer cells rely on a single protein, ATR, to cope with the ensuing DNA damage." (PMID 35008191, 2021). "Here we investigated how TopBP1 overexpression may affect the ATR/Chk1 activation in cancer cells." (PMID 33556369, 2021). "In particular, the hypersensitivity of ATM-mutated cancers to ATR inhibition could be driven by over-lapping and redundant functions of ATM and ATR kinases, given that there are over 700 suggested ATM/ATR substrates harbouring S/T-Q motifs." (PMID 34329458, 2021). "Interestingly, ATR inhibition increases the effectiveness of PARP inhibitors in cancer therapy, supporting this hypothesis." (PMID 34829691, 2021). "Together, these findings identify evolutionarily conserved ATM, ATR, and Mec1ATR residues involved in diverse aspects of the enzyme function and provide fresh insights into the elusive genotype-phenotype relationships in ATM/ATR and their cancer-associated variants." (PMID 33742106, 2021). "However, this ss G-overhang must also be protected from engaging in the activation of an ATR-dependent DNA damage signal that would otherwise elicit illegitimate homology directed repair, generating aberrant chromosome fusions that might be cancer promoting." (PMID 34535663, 2021). "Thus, to potentiate the therapeutic effects of gemcitabine and cisplatin specifically on a molecular level, we focused our attention, in a next step, on the ATM/ATR pathway that contributes to the DNA damage response in cancer and upon various types of chemotherapies, including antimetabolites." (PMID 34439352, 2021). "However, a few recent studies challenged the specificity of ATR inhibitors towards ALT cancers." (PMID 34069193, 2021). "Similarly, the ATR levels in cancer cells were correlated with patient survival." (PMID 32414408, 2020). "Thus, targeting ATR has been proposed as a potential cancer therapy." (PMID 33137164, 2020). "Activation of extraembryonic features in response to ATR in early stages of cellular transformation could be a major outcome of RS induced by oncogene activity in cancer cells and would provide an additional rationale for the potent tumor suppressive effect of ATR inhibitors." (PMID 32163370, 2020).